FCRL5 (Fc receptor like 5)
Diseases named in the same sentence as FCRL5 in open-access papers (continued):
Sharing a sentence is not in itself a finding about the gene and the disease.
COVID-19 (4 papers, 2021 to 2023). A disease caused by infection with severe acute respiratory syndrome coronavirus 2. "In recovered COVID-19 patients, memory B cells present 1–3 months after symptom onset are also found to express FcRL5 and T-bet, suggesting that these markers may delineate a subset of long-lived memory B cells against SARS-CoV-2." (PMID 34936684, 2021). "Here, we observed an increase in the percentage of spike-specific IgG+ B cells that expressed T-bet and FcRL5 shortly after recovery from non-severe COVID-19, but not after severe COVID-19." (PMID 34936684, 2021). "Among DN cells, DN1 (FcRL5- CXCR5+) B cells were the dominant subset in both groups of recovered COVID-19 patients, and we did not detect significant differences in the frequencies of DN1, DN2 (FcRL5+ CXCR5-), and DN3 (FcRL5- CXCR5-) B cells between the two groups." (PMID 34936684, 2021).
anemia (3 papers, 2019 to 2021). A reduction in the number of red blood cells, the amount of hemoglobin, and/or the volume of packed red blood cells. "In Plasmodium falciparum patients with anemia, we show that atypical memory FcRL5+T-bet+ B-cells are expanded and associate both with higher levels of anti-PS antibodies in plasma and with the development of anemia in these patients." (PMID 31713516, 2019). "The P. falciparum-infected erythrocytes activate the FcRL5+T-bet+ B cells to release the anti-PS autoantibodies, which then bind to uninfected erythrocytes and induce the erythrocyte clearance, leading to anemia." (PMID 34395313, 2021). "In this study, we focused on measuring the levels of atypical FcRL5+T-bet+ B-cells in the circulation of P.-falciparum-infected returned travelers and its relation to autoantibodies and anemia development." (PMID 31713516, 2019). "Our results show that atypical FcRL5+T-bet+ B-cells are greatly expanded in acute malaria in P.-falciparum-infected patients and correlate with both anemia development and plasma anti-PS antibody levels in these patients." (PMID 31713516, 2019). "Importantly, we have reported how P. falciparum-induced AtMBCs, characterized by double positivity of FcRL5 and T-bet, are able to secrete anti-PS antibodies in vitro and how they correlate with anemia in first-time infected P. falciparum patients." (PMID 32687495, 2020). "Our results in human samples also provide evidence that FcRL5+T-bet+ B-cells correlate with anemia." (PMID 31713516, 2019). "The atypical FcRL5+T-bet+ B cells were found to be expanded greatly in acute malaria in the circulation of P. falciparum-infected returned travelers and this was correlated with both the development of anemia and the plasma anti-phosphatidylserine (PS) autoantibodies in these patients." (PMID 34395313, 2021).
microscopic polyangiitis (3 papers, 2020 to 2024). Microscopic polyangiitis (MPA) is an inflammatory, necrotizing, systemic vasculitis that affects predominantly small vessels (i.e. small arteries, arterioles, capillaries, venules) in multiple organs. "FcRL5 is a biomarker of B cell lineage associated with maintenance of complete remission among patients treated with rituximab in granulomatosis with polyangiitis and microscopic polyangiitis." (PMID 32841219, 2020). "This study investigated baseline expression of FCRL5 as a potential biomarker of clinical response to RTX in granulomatosis with polyangiitis (GPA) and microscopic polyangiitis (MPA)." (PMID 32841219, 2020).
systemic lupus erythematosus (3 papers, 2022 to 2025). An autoimmune multi-organ disease typically associated with vasculopathy and autoantibody production. "In systemic lupus erythematosus (SLE), the DN B cells express CD11c, FcRL5 and T-bet, markers largely overlapping with those expressed during infection." (PMID 35812395, 2022).
Burkitt lymphoma (2 papers, 2016 to 2021). A rare form of malignant mature B-cell non-Hodgkin lymphoma. "For instance, expression of various FCRLs is up-regulated in Diffuse Large B-cell Lymphoma (DLBCL), FL, and CLL, while FCRL5 was shown to be upregulated in Burkitt Lymphoma (BL)." (PMID 27446638, 2016).
Encephalopathy (2 papers, 2023). Encephalopathy is a term that means brain disease, damage, or malfunction. "Consistently, in a pediatric COVID‐19 patient who has severe symptoms and encephalopathy, FCRL5 is also highly expressed in tissue‐like B cells." (PMID 38020713, 2023).
Graves disease (2 papers, 2011 to 2021). Graves' disease is an autoimmune disorder that leads to overactivity of the thyroid gland (hyperthyroidism).It is caused by an abnormal immune system response that causes the thyroid gland to produce too much thyroid hormones. "rs11264798 located in intron 8 of FCRL3, and rs10489678 in FCRL5, have been previously associated with Graves' disease." (PMID 21829393, 2011).
hairy cell leukemia (2 papers, 2016 to 2023). Hairy cell leukemia (HCL) is a rare type of leukemia in which abnormal B-lymphocytes are present in the bone marrow, spleen and peripheral blood. "In hairy cell leukemia, there is also a phenomenon in which FCRL5 expression caused IgG and IgA isotype switching in addition to a group of abnormal cells that co-expressed multiple Ig isotypes." (PMID 27446638, 2016).
Hepatitis C (2 papers, 2020 to 2022). "Markedly high FCRL2, FCRL3, and FCRL5 were identified in the context of Hepatitis C vaccination." (PMID 32747654, 2020).
influenza (2 papers, 2021 to 2025). An acute viral infection of the respiratory tract, occurring in isolated cases, in epidemics, or in pandemics; it is caused by serologically different strains of viruses (influenzaviruses) designated A, B, and C, has a 3-day incubation period, and usually lasts for 3 to 10 days. "Interestingly, FcRL5 was recently proposed to be a marker of durable B cell memory in response to tetanus and influenza immunization." (PMID 34758841, 2021).
melanoma (2 papers, 2024 to 2025). A malignant, usually aggressive tumor composed of atypical, neoplastic melanocytes. "FCRL4+FCRL5+ B cell signature was also a good prognostic factor in melanoma." (PMID 40990023, 2025).
multiple sclerosis (2 papers, 2021 to 2023). A progressive autoimmune disorder affecting the central nervous system resulting in demyelination. "There are reports that single nucleotide variants in the FCRL5 gene increase an individual’s predisposition to multiple sclerosis or SLE." (PMID 36949950, 2023). "We aimed to test, for the first time, whether some of the single nucleotide variants in the FCRL5 gene were associated with multiple sclerosis (MS) susceptibility and clinical manifestations in the Polish population." (PMID 33889124, 2021).
sarcoidosis (2 papers, 2023 to 2024). Sarcoidosis is a multisystemic disorder of unknown cause characterized by the formation of immune granulomas in involved organs. "The higher FCRL5+ B cell percentage in sarcoidosis was associated with progressive lung involvement." (PMID 36949950, 2023). "Conversely, a patient with sarcoidosis exhibiting a low percentage of FCRL5+ B cells, bilateral hilar lymphadenopathy, and small nodules on CT demonstrated marked improvement on follow-up." (PMID 36949950, 2023). "While we did not observe any differences in CD11c+ DN B cells between individuals with IPF, CTD-ILDs, and sarcoidosis, there was a tendency for FCRL5+ B cells to increase in CTD-ILDs relative to the other groups." (PMID 36949950, 2023). "Using mass cytometry analysis of immune cell subsets in bronchoalveolar lavage fluid (BALF), the analysis of T and B cells revealed increased levels of CXCR3+ CD226+ CD4+ T cells and the presence of FCRL5+ B cells in sarcoidosis patients with advanced lung lesions." (PMID 39896815, 2024). "FCRL5+ B cells were mostly IgG+ or IgA+ in each group (IPF: 75%, CTD-ILD: 80.3%, Sarcoidosis: 91.7%), suggesting that these FCRL5+ B cells were class-switched B cells." (PMID 36949950, 2023). "These FCRL5+ B cells were also present in the patient with AEx-IPF and sarcoidosis with advanced lung lesions." (PMID 36949950, 2023).
autoimmune thyroid disease (1 paper, 2021). Inflammatory disease of the thyroid gland due to autoimmune responses leading to lymphocytic infiltration of the gland. "However, the rs2012199 and rs6679793 SNVs of the FCRL5 gene investigated in our study have been associated only with an autoimmune thyroid disease so far." (PMID 33889124, 2021).
dengue (1 paper, 2019). "Even though percentages of FcRL4+ B cells were low in naïve B cells of dengue positive patients, we did not evaluate other subsets of atypical B cells such as FcRL5+, CD11c+T-bet+, T-bethiCD85jhi, or CD21−/loCD27− B cells, which might affect our results." (PMID 31736948, 2019).
fibrosis (1 paper, 2022). the formation of excess fibrous connective tissue in an organ or tissue in a reparative or reactive process. "We analyzed the associations of FCRL5 mRNA expression levels and demographic and clinical parameters in fibrosis and non-fibrosis patients, respectively." (PMID 36160227, 2022). "The mRNA relative expression levels of FCRL5 in patients with liver fibrosis were significantly higher than those in the non-fibrosis group (t = 13.456, p < 0.001)." (PMID 36160227, 2022). "We compared the demographic and clinical characteristics of the fibrosis patients with different FCRL5 gene genotypes." (PMID 36160227, 2022). "The mRNA relative expression levels of FCRL5 in patients with liver fibrosis were 0.83 ± 0.13, which were significantly higher than those in the non-fibrosis group (0.63 ± 0.09), with a statistically significant difference (t = 13.456, p < 0.001)." (PMID 36160227, 2022). "The fibrosis patients carried TT or CT genotype of rs6692977 had significantly higher FCRL5 mRNA expression levels than those carried CC genotype (t = 2.859, p = 0.005)." (PMID 36160227, 2022). "Additionally, to verify the influence of FCRL5 SNPs on gene mRNA expression, we compared the FCRL5 mRNA expression levels between fibrosis patients with different genotypes." (PMID 36160227, 2022). "Furthermore, we observed that in the fibrosis group, BMI was positively correlated with FCRL5 mRNA expression levels." (PMID 36160227, 2022). "In addition, this study observed that the mRNA expression levels of FCRL5 in CHB patients with liver fibrosis were significantly higher than those in non-fibrosis patients." (PMID 36160227, 2022). "Whether liver fibrosis occurred was considered as the state variable (non-fibrosis = 0, fibrosis = 1), and FCRL5 mRNA expression, APRI and FIB-4 index were regarded as test variables, respectively." (PMID 36160227, 2022).
liver cancer (1 paper, 2022). An epithelial or non-epithelial malignant neoplasm that arises from the liver. "The mechanism may be related to the high expression of matrix metalloproteinase-9 and vascular endothelial growth factor induced by FCRL5 in liver cancer cells." (PMID 36160227, 2022).
liver fibrosis (1 paper, 2022). "In conclusion, FCRL5 gene rs6692977 polymorphisms and mRNA expression levels are associated with liver fibrosis in CHB patients." (PMID 36160227, 2022). "To confirm the results that FCRL5 gene polymorphisms were associated with liver fibrosis, we measured the FCRL5 mRNA expression levels in all subjects using the qRT-PCR assay." (PMID 36160227, 2022). "In this study, we explored the associations of two FCRL5 polymorphisms (rss6427384 and rs6692977) and FCRL5 mRNA expression with liver fibrosis in CHB patients." (PMID 36160227, 2022). "Therefore, we speculated that rs6692977 TT or CT variants of the FCRL5 gene could up-regulate gene expression levels, and thus participate in the pathogenesis of liver function injury and liver fibrosis." (PMID 36160227, 2022). "The ROC curve results of FCRL5 mRNA expression levels for the predictive value of liver fibrosis showed that AUC was 0.896, with sensitivity and specificity of 73.7% and 93.3%." (PMID 36160227, 2022). "Although the efficacy of FCRL5 mRNA expression levels in predicting liver fibrosis was mediocre, it can provide a new perspective for predicting liver fibrosis by non-invasive method." (PMID 36160227, 2022). "Thirdly, we did not conduct functional experiments to investigate the exact mechanisms of FCRL5 gene variations in the occurrence and development of liver fibrosis." (PMID 36160227, 2022). "Hence, in the treatment of liver fibrosis, FCRL5 levels may also need to be controlled to achieve better outcomes." (PMID 36160227, 2022). "The mRNA expression levels of FCRL5, APRI, and FIB-4 index showed predictive efficacy in liver fibrosis with cut-off values of 0.75 (AUC = 0.896, 95% CI = 0.856–0.935), 0.45 (AUC = 0.852, 95% CI = 0.802–0.902) and 1.84 (AUC = 0.765, 95% CI = 0.703–0.826), respectively." (PMID 36160227, 2022).
lymph node metastasis (1 paper, 2022). "GPRIN1 was found to be significantly high in patients with lymph node metastasis, while FCRL5 was low expressed in patients with the clinical stage, lymph node metastasis, and distant metastasis." (PMID 35903698, 2022). "Besides, high expression of GPRIN1 is highly involved in the lymph node metastasis, and FCRL5 with not only lymph node metastasis but also distant metastasis and the clinical stage of LUAD patients." (PMID 35903698, 2022).
parasitemia (1 paper, 2015). "It is possible that immune activation associated with this state of asymptomatic parasitemia in part drives the accumulation of atMBCs and affects aspects of their phenotype, such as the expression of FCRL5." (PMID 25993340, 2015).
pemphigus vulgaris (1 paper, 2022). Pemphigus is a group of chronic autoimmune skin diseases characterized by blister formations on the outer layer of the skin and the mucous membranes. "We also observed that most CD11c+ DN B cells were FcRL5+ cells in Dsg3-specific B cells from pemphigus vulgaris patients." (PMID 35983042, 2022).
periodontitis (1 paper, 2021). An acute or chronic inflammatory process that affects the tissues that surround and support the teeth. "Four common crosstalk genes between periodontitis and DS were acquired, i.e., CD19, FCRL5, FCRLA, and HLA-DOB, of which the latter had the highest prediction accuracy." (PMID 34545294, 2021).
Splenomegaly (1 paper, 2023). Abnormal increased size of the spleen. "The Fcrl5 Tg mice showed more progressive splenomegaly (data not shown) and increased numbers of CD19+ B cells and CD4+ T cells than WT mice." (PMID 37841260, 2023).
vasculitis (1 paper, 2020). "Furthermore, FCRL5 expression appears to have a predictive value independent of other response-predictive factors such as type of vasculitis, serology, or presence of relapsed disease in a multivariate analysis." (PMID 32841219, 2020).
viral infection (1 paper, 2022). "Given that DN2 cells express the FcRL5 inhibitory receptor and expression is unchanged with viral infection, we wondered whether DN3 cells also express this receptor." (PMID 36131937, 2022). "This suggests that DN2 cells naturally have the largest capacity to signal through the BCR compared to other DN subsets, a process which may be independent of traditional inhibitory receptors (CD22, CD72, FcRL5) and/or that the function of inhibitory receptors is impaired during viral infection." (PMID 36131937, 2022). "Overall, it is clear that viral infection modulates the phenotype of the novel DN3 subset such that these cells have reduced BAFFR and CD86 but elevated levels of FcRL5, CD22, and CD69 during severe disease." (PMID 36131937, 2022).
vivax malaria (1 paper, 2022). "The overexpression of FcRL5 on IgG+ T-bethi atypical MBCs in vivax malaria might be part of a feedback mechanism which downregulates the hyperactivated state of atypical MBCs, or they may be markers of durable and robust responses to re-infection as previously proposed in P. falciparum studies." (PMID 35318412, 2022).
tumor (25 papers, 2015 to 2025). "Taken together, our analysis suggests that FCRL4+FCRL5+ B cells are associated with anti-tumor activity and a positive response to combined therapy." (PMID 36869384, 2023). "In co-culture, FCRL5 CAR-T cells displayed enhanced tumor-killing ability at lower effector:target (E:T) ratios, superior recognition of NCI-H929 and FCRL5+MM1.S cells and resulted in enhanced cell death than BCMA CAR-T cells." (PMID 38212320, 2024). "For example, for patient 27522, the expression of FCRL5 in the primary tumor, remission, and recurrence were consistent with the tumor burden, spanning six key time points." (PMID 38212320, 2024). "In the NCI-H929-luc subcutaneous model, both FCRL5-targeted CAR-T cell treatments initially attenuated tumor progression; however, FCRL5 CAR-T/IL-15 demonstrated enhanced therapeutic sustainability, with mice experiencing prolonged survival until the conclusion of the study." (PMID 38212320, 2024). "Moreover, real-time cellular analysis (RTCA) corroborated the tumor-lytic potential of FCRL5 CAR-T cells in engineered FCRL5-overexpressing HeLa cells (HeLa-FCRL5)." (PMID 38212320, 2024). "Several of the top-ranked genes–MS4A1 (CD20), FCRL5 and CD79A–are closely associated with B-cell functions, suggesting that variations in humoral and antigen-presenting activity may critically modulate anti-tumor immunity." (PMID 40745034, 2025). "However, the tumor suppression mediated by FCRL5 CAR-T cells was temporary." (PMID 38212320, 2024). "FCRL5 CAR-T cells suppressed the growth of FCRL5+MM1.S-luc xenografts, thereby extending the lifespan of tumor-bearing mice." (PMID 38212320, 2024). "Recently, numerous BsAbs have been developed for MM treatment, with ideal tumor antigen targets including BCMA, G protein-coupled receptor 5D (GPRC5D), Fc receptor-like 5 (FCRL5), and CD38." (PMID 38280847, 2024). "Both in vitro and xenograft models displayed that FCRL5 CAR-T cells incorporating IL-15 exhibited potent antitumor efficacy, effectively inhibiting the proliferation of MM cells and leading to remarkable tumor suppression." (PMID 38212320, 2024). "The data suggest that in the TME of immunotherapy responders, FCRL4+ FCRL5+ B cells are driven by IFNα, TNF, and IL27 signals, and Tfhs are activated by these B cells to enhance anti-tumor immunity through secreting IL21." (PMID 36869384, 2023). "Furthermore, eight target genes (COL4A3, FAM30A, FCRL5, MDM4, SYNE2, TNFRSF13C, TPTEP2, VAMP1) were systematically positively correlated with ESR2 expression patterns in tumor types with low ESR2 expression as a prognostic factor concerning OS or DFS." (PMID 39201394, 2024). "FCRL5/IL-15 CAR-T cells promoted a shift towards the TCM phenotype while reducing PD-1 exhaustion, which may facilitate more durable and potent anti-tumor responses, thus potentially overcoming the limitations of BCMA-targeted therapy." (PMID 38212320, 2024).